FBP1 (fructose-bisphosphatase 1)
Diseases named in the same sentence as FBP1 in open-access papers (continued):
Sharing a sentence is not in itself a finding about the gene and the disease.
lung adenocarcinoma (10 papers, 2021 to 2025). A carcinoma that arises from the lung and is characterized by the presence of malignant glandular epithelial cells. "GBE1 was found to cause promoter methylation of the FBP1 gene in lung adenocarcinoma cells through the NF-κB pathway, which decreased the expression of the FBP1 protein." (PMID 36900384, 2023). "The restoration of FBP1 expression in lung adenocarcinoma effectively hindered cell proliferation and invasion under hypoxic conditions in vitro, while also suppressing tumor growth in vivo." (PMID 38349431, 2024). "Glycogen Branching Enzyme 1 (GBE1)-mediated FBP1 suppression via promoter methylation contributes to tumor progression in lung adenocarcinoma (LUAD)." (PMID 35978816, 2022). "As a result of their pancancer pattern, the relationship between ALDOA and FBP1 in patient prognosis is reversed, particularly in lung adenocarcinoma (LUAD) and liver hepatocellular carcinoma (LIHC)." (PMID 35404841, 2022). "Previous studies reported that hypoxia-induced GBE1 expression promotes tumor progression by repressing FBP1 activities in lung adenocarcinoma." (PMID 34637697, 2021). "Our previous investigation confirmed the down-regulation of FBP1 in lung adenocarcinoma, where it functioned as a tumor suppressor by inhibiting proliferation and epithelial–mesenchymal transition (EMT) in lung adenocarcinoma cells." (PMID 38349431, 2024). "In lung adenocarcinomas, GBE1 methylates the promoter of FBP1 through the NF-κB pathway and therefore decreases FBP1 expression." (PMID 36900384, 2023). "Our study found that FBP1 elevation by GBE1 knockdown suppressed the basal glycolytic rate and the glycolytic reserve capacity of glioma cells; this parallels a previous study on lung adenocarcinoma." (PMID 36900384, 2023). "In addition, we will further investigate the impact of downregulating or promoting FBP1, SBK1, and AURKA expression in PC9 cells on lung adenocarcinoma in the future." (PMID 37737707, 2023). "Besides, it was demonstrated that LINC01419 could reduce FBP1 levels by recruiting EZH2, thereby promoting the proliferation and stemness of lung adenocarcinoma (LUAD) cells." (PMID 40100307, 2025). "It has also been shown that methylation of the FBP1 promoter, which can be induced by other pathways such as the nuclear factor-kappa B (NF-κB) pathway, has also been observed in other types of cancer, such as non-small cell lung cancer (NSCLC) and lung adenocarcinoma (LUAD)." (PMID 39997396, 2025). "However, unlike lung adenocarcinoma, GBE1 knockdown increased oxidative phosphorylation in glioma cells and was difficult to reverse with FBP1 knockdown." (PMID 36900384, 2023).
lactic acidosis (8 papers, 2021 to 2025). Metabolic acidosis characterized by the accumulation of lactate in the body. "Here we identify compound heterozygous missense mutations of FBP1, c.491G>A (p.G164D) and c.581T>C (p.F194S), in an adult patient with hypoglycemic lactic acidosis." (PMID 37507476, 2023). "Fructose-1,6-bisphosphatase (FBPase) deficiency, caused by an FBP1 mutation, is an autosomal recessive disorder characterized by hypoglycemic lactic acidosis." (PMID 37507476, 2023). "Decreased gluconeogenesis is a phenomenon often related to increased glycolytic activity, and loss of a key gluconeogenesis regulator FBP1 has previously been shown to induce glycolysis, and lead to hyperglycemia and lactic acidosis." (PMID 33668151, 2021). "Fbp1 deficiency results in ketotic hypoglycaemia and lactic acidosis." (PMID 33960626, 2021).
renal cell carcinoma (8 papers, 2008 to 2025). "The correlation between FBP1/FBP3, c-myc and high proliferation rate in renal cell carcinoma provides strong in vivo support for the suggested role of FBP1 and FBP3 as activators of c-myc." (PMID 19087307, 2008). "Staining of FBP1 was evaluable in 104 renal cell carcinomas." (PMID 19087307, 2008). "Particularly, FBP1 showed DNA hypermethylation status in promoter regions in both KIRC and normal ones, which is even relatively higher in normal than that in KIRC, implying that FBP1 depletion in renal cell carcinoma is not caused by DNA hypermethylation in promoter." (PMID 35978816, 2022). "Likewise, the gluconeogenetic enzyme fructose-1,6-bisphosphatase 1 (FBP1), which was previously shown to oppose renal cell carcinoma (ccRCC) progression was more than 200-fold decreased in renal oncocytomas." (PMID 29285300, 2017). "Here, we have analyzed the expression of FBP1 (as the family progenitor and a moderate transcriptional activator) and FBP3 (as the strongest transcriptional activator of this family,) as well as c-myc in renal cell carcinomas (RCC), prostate (PCA) and urothelial cancers of the urinary bladder." (PMID 19087307, 2008).
glioma (7 papers, 2021 to 2025). A benign or malignant brain and spinal cord tumor that arises from glial cells (astrocytes, oligodendrocytes, ependymal cells). "GBE1 downregulates FBP1 expression through the NF-κB pathway, causing a shift in the glucose metabolism pattern of glioma cells to glycolysis, enhancing the Warburg effect, and promoting the development of glioma." (PMID 36900384, 2023). "For example, there is a positive correlation between the expression of FUBP1 and c-MYC in glioma and high expressions of FBP1 and c-MYC are associated with poor prognosis." (PMID 34116677, 2021). "However, the knockdown of FBP1 reversed the inhibition of glycolysis caused by GBE1 knockdown, indicating that the increased expression of FBP1 is an important reason for the impaired glycolysis of glioma cells caused by GBE1 knockdown." (PMID 36900384, 2023). "Inspired by this, a glucose metabolism‐related gene (GMG)‐based model, including LDHA, GUSB, GLB1, GALM, and FBP1, was proposed based on protein‒protein interaction analysis to predict the prognosis of patients with glioma." (PMID 39830021, 2025). "In glioma, FBP1 is involved in the promoting effects of glycogen branching enzyme 1 on the aerobic glycolysis of the cancer." (PMID 39902328, 2025). "In contrast, knockdown of the elevated FBP1 based on GBE1 knockdown restored glioma cell proliferation and impaired tumor biological behavior." (PMID 36900384, 2023). "Our study confirmed that in glioma cells, FBP1 expression was significantly elevated after GBE1 knockdown." (PMID 36900384, 2023). "Our study found that knockdown of FBP1 promoted the proliferation, migration, and invasion of glioma cells, while overexpression of FBP1 in glioma cells significantly inhibited the malignant phenotype of glioma cells, which paralleled the previous study." (PMID 36900384, 2023). "Given that previous results showed GBE1 negatively regulated FBP1 expression in U251 cells, to further verify the role of FBP1 in gliomas, we constructed U251 cells with FBP1 knockdown (sh-FBP1) and FBP1 overexpression (oe-FBP1)." (PMID 36900384, 2023). "We then demonstrated through cellular and animal experiments that GBE1 influences FBP1 expression through the NF-κB pathway, which affects the glucose metabolism pattern of glioma cells and promotes the Warburg effect to drive tumor progression." (PMID 36900384, 2023). "Increasing FBP1 expression helps to suppress these malignant phenotypes in glioma cells." (PMID 36900384, 2023). "Our results showed that the NF-κB pathway was inhibited following GBE1 knockdown in glioma cells, accompanied by elevated FBP1 expression; this paralleled the effects of single NF-κB pathway inhibitors, suggesting that regulation of FBP1 expression by GBE1 via NF-κB is also applicable in glioma." (PMID 36900384, 2023). "Collectively, GBE1 reduces FBP1 expression through the NF-κB pathway, shifting the glucose metabolism pattern of glioma cells to glycolysis and enhancing the Warburg effect to drive glioma progression." (PMID 36900384, 2023). "Moreover, GBE1 promotes glioma progression by enhancing aerobic glycolysis through the inhibition of fructose–bisphosphatase 1 (FBP1), which reveals GBE1 as a potential target for glioma therapy." (PMID 36900384, 2023). "However, it was noteworthy that a study in gliomas reported that the expression of FBP1 is positively relevant to the c-Myc level and tumor proliferation." (PMID 35127693, 2021). "To further investigate why FBP1 inhibited glioma progression, considering the important role of FBP1 in glucose metabolism, we speculated that the glucose metabolic system of glioma cells was affected after GBE1 knockdown, which in turn inhibited glioma progression." (PMID 36900384, 2023). "It was consistent with our results, indicating that FBP1 might play different functions in gliomas." (PMID 35127693, 2021).
glioma (continued). "Each one of the two correlation coefficients manifested that both SPP1 and HMOX1 were consistently co‐expressed with 20 genes in glioma samples, such as VAMP8, RAC2, MSR1, CAPG and FBP1." (PMID 40495644, 2025). "In glioma, we also observed that knockdown of GBE1 significantly inhibited the phosphorylation level of p65 protein, accompanied by elevated FBP1 expression." (PMID 36900384, 2023). "Further studies revealed that glioma cells with knockdowns of both GBE1 and FBP1 showed a significant rebound in migration, invasion, vascularization, and colony formation ability compared with single GBE1 knockdowns." (PMID 36900384, 2023). "In gliomas, GBE1 reduces the expression of FBP1 through the NF-κB pathway." (PMID 40100307, 2025). "To investigate whether GBE1 regulates glioma progression through FBP1, we constructed U87 and U251 cell lines in which both GBE1 and FBP1 were knocked down and observed whether the inhibition of glioma by single GBE1 knockdown could be reversed." (PMID 36900384, 2023). "And FBP1 levels were significantly elevated after QNZ treatment compared to vehicle control, which paralleled the effect of GBE1 knockdown, indicating that the conclusion that GBE1 regulates FBP1 expression through the NF-κB pathway is also applicable in gliomas." (PMID 36900384, 2023).
colorectal cancer (6 papers, 2017 to 2025). A primary or metastatic malignant neoplasm that affects the colon or rectum. "FOXC1 exhibits an enhanced expression in colorectal cancer; it directly binds to the promoter region of the FBP1 gene and inhibits transcriptional activity, promoting colorectal cancer growth by enhancing the Warburg effect." (PMID 40100307, 2025). "FOXC1 enhances cell growth and reduces lactate generation and glucose usage in colorectal cancer by suppressing FBP1 expression." (PMID 39093497, 2024). "Gluconeogenic genes, such as phosphoenolpyruvate carboxykinase 2 (PCK2) and FBP1, are less expressed when AF9 is deleted, promoting glucose depletion and colorectal cancer." (PMID 40100307, 2025). "In colorectal cancer, FOXC1 directly binds to the promoter region of the FBP1 gene and negatively regulates its transcriptional activity, whereas, AF9 reduces fbp1 transcription by targeting the FBP1 promoter through recognition of H3K9ac." (PMID 40100307, 2025). "In addition, FBP1 is a glycolytic enzyme, and a lack of FBP1 contributes to the appearance of aerobic glycolysis enhancement in colorectal cancer." (PMID 36879346, 2023).
hyperglycaemia (6 papers, 2010 to 2025). "In vivo PTTs provided strong evidence that salicylate suppresses hyperglycaemia in HFD through a FBP1‐dependent mechanism." (PMID 40400417, 2025). "The inhibition of Fbp1 by its inhibitor attenuated hyperglycemia in Zucker diabetic fatty rats." (PMID 34206641, 2021). "Excessive HGP is a major contributor to both fasting and postprandial hyperglycaemia and is suppressed by insulin by inhibiting the expression of gluconeogenic enzymes, namely phosphoenolpyruvate carboxykinase 1 (Pck1), fructose-1,6-bisphosphatase (Fbp1) and glucose-6-phosphatase." (PMID 20977585, 2010). "Unexpectedly, qPCR showed reduced expression of G6PC, PCK1, FBP1 with the down‐regulation of SMC5, suggesting that hepatic gluconeogenesis is not the cause of hyperglycaemia." (PMID 36627765, 2023).
type 2 diabetes (6 papers, 2020 to 2025). "Kaur et al9 reported that Fbp1 can be considered a potential target for the treatment of type 2 diabetes." (PMID 33960626, 2021). "Notably, Fbp1 inhibitors have been reported as effective in the management of type 2 diabetes." (PMID 33960626, 2021). "Metformin (N,N-dimethylbiguanide) activity relies also on inhibition of fructose-1-6- bisphosphatase-1 (FBP1) by regulating hepatic glucose production, reducing HGF and normalizing blood glucose levels in hyperglycemic type 2 diabetics." (PMID 32516941, 2020).
viral infection (6 papers, 2012 to 2025). "To further elucidate the role of FBP in viral infection, we manipulated the expression of FBP1 and PFK1, which respectively regulate the consumption and production of FBP in cells." (PMID 39693295, 2024). "Both PmFortilin and FBP1 transcripts have been show to be up regulated during a viral infection, thus implying a role in a defense mechanism against viruses." (PMID 22428011, 2012). "Pharmacological inhibition of SAM and FBP1 also reduced virus infection at late lifecycle stages." (PMID 40517242, 2025). "To further investigate the impact of FBP on viral infection, we generated various FBP1 mutants: an enzyme-deletion mutant (FBP1-G260R), a nuclear localization mutant (FBP1-NLS), and a combination of both features (FBP1-NLS-G260R)." (PMID 39693295, 2024). "We found it to be present at high levels during an onset of viral infection in P. monodon and based on a yeast two-hybrid screening assay and GST-pulldown, we further found Fortilin to interact with a previously unknown protein, named Fortilin Binding Protein 1 (FBP1) (Accession No: EU435133.1)." (PMID 22428011, 2012).
bladder cancer (5 papers, 2008 to 2025). "Low expression of FBP1 is associated with the clinical stages of bladder cancer and is closely related to lower survival rates in bladder cancer patients (in whom there is more frequent urinary epithelial recurrence and metastasis)." (PMID 39609317, 2024). "Overall, these results suggest that DNA hypermethylation at FBP1 and HPGD loci is associated with their reduced expression, aligning with disease aggressiveness and poor survival in bladder cancer patients." (PMID 40626022, 2025). "To this end, we investigated the correlation between DNA methylation and expression of genes from Metab-GS in bladder cancer, and found high inverse correlation (>−0.50) between DNA methylation and expression of tumor suppressor metabolic hubs, FBP1 and HPGD." (PMID 40626022, 2025). "After the overexpression of BRM, the expression of almost all glycolytic genes (including PKM2), except fructose-1,6-bisphosphatase (FBP1), has been shown to increase in T24 bladder cancer cells, leading to increased glucose uptake." (PMID 39609317, 2024). "Compared to that in T24 bladder cancer cells, the expression of FBP1 is greater at both the protein and transcript levels in 5637 bladder cancer cells, resulting in decreased glucose uptake." (PMID 39609317, 2024). "BRM plays an important role in glycolysis in bladder cancer cells by affecting the glycolytic process in bladder cancer cells through the influence of the key enzyme of glycolysis, FBP1, which in turn affects tumor phenotype." (PMID 39609317, 2024). "Additionally, the expression of SMARCA2 influences the expression of Fructose‐1,6‐bisphosphatase 1 (FBP1), and the low expression of FBP1 is related to the clinical stage of bladder cancer, more frequent recurrence, and metastasis." (PMID 39779467, 2025). "Therefore, the expression of FBP1 can serve as a prognostic marker for bladder cancer patients." (PMID 39779467, 2025). "Our findings demonstrate a strong inverse correlation between DNA methylation levels at FBP1 and HPGD loci and their gene expression, thereby linking epigenetic dysregulation directly to the tumor aggressiveness in bladder cancer." (PMID 40626022, 2025). "FBP1, FBP3 and c-myc expression was studied in 105 renal cell, 95 prostate and 112 urinary bladder carcinomas by immunohistochemistry using tissue microarrays." (PMID 19087307, 2008). "In bladder cancer, c-Myc correlated to tumor grading (WHO 2004: correlation coefficient 0.267, p = 0.003), but did not correlate to FBP1 or FBP3 expression or Ki-67 fraction." (PMID 19087307, 2008).
cryptococcosis (5 papers, 2018 to 2025). An acute or chronic, localized or disseminated infection by Cryptococcus neoformans. "Given the importance of CD4+ T cells in defense against cryptococcosis, we next examined the differentiation of Cryptococcus-specific CD4+ T cells in mice infected with Fbp1-deficient or -sufficient yeast." (PMID 29317510, 2018).
non-small cell lung carcinoma (5 papers, 2015 to 2025). A group of at least three distinct histological types of lung cancer, including non-small cell squamous cell carcinoma, adenocarcinoma, and large cell carcinoma. "In non-small cell lung cancer cells, OGT overexpression following glutamine deprivation abolishes fructose-1,6-bisphosphatase 1 (FBP1) phosphorylation and enhances β-oxidation gene transcription via FBP1 O-GlcNAcylation, thus promoting cell proliferation." (PMID 39285476, 2024).